CD28 (CD28 molecule)
Diseases named in the same sentence as CD28 in open-access papers (continued):
Sharing a sentence is not in itself a finding about the gene and the disease.
COVID-19 (continued). "Collectively, we demonstrated that upon activation with anti-CD3/CD28, T-cell immune profiles in COVID-19 patients who recovered for 6 months may still be in a potentially hypersensitive state." (PMID 38424104, 2024). "This discrepancy can probably be attributed to the fact that Tc were stimulated with αCD3/CD28 polyclonal activation under normoxic conditions which may result in nulling of any potential metabolic differences present in COVID-19." (PMID 37029220, 2023). "Post-COVID-19 presented a lower percentage of Treg cells (p adj = 0.03) and altered markers of lymphocyte activation and exhaustion (lower CD28 expression in CD8+ T cells (p adj = 0.014), whereas CD4+T cells showed higher PD1 expression (p adj = 0.037)) compared with the control group." (PMID 37753077, 2023). "Also, CD8+ T cells from individuals who had previous COVID-19 showed a lower expression of the co-stimulatory molecule CD28 compared with control." (PMID 37753077, 2023). "The CD27+CD28+ subset of T cells, commonly referred to as naïve T cells, play a critical role in mounting an effective immune response against novel viral infections such as COVID-19 or in response to vaccination." (PMID 37465793, 2023). "The interrelationship of immune cells in COVID-19 was intrinsically identified, whereby T cells secreting IL-2, IL-4, and IL-17A were enriched among CD28+ and CD57− cells and cells secreting perforin/granzyme B/IFN-γ/tumor necrosis factor alpha (TNF-α)-expressed markers of terminal differentiation." (PMID 34488453, 2021). "Other Food and Drug Administration-approved antiinflammatory drugs tested in models of SEB TSS may also be effective, including CTLA4-Ig which can inhibit CD28 costimulation, and the mammalian target of rapamycin (mTOR) inhibitor rapamycin, which is already in use for COVID-19." (PMID 32989130, 2020). "In COVID-19 patients with EBV reactivation, the degree of expression of the T-cell co-stimulatory CD28 and co-expression of CD28 and the integrin CD11a was diminished on CD8 T-cells." (PMID 42002663, 2026). "Metacluster #1 was more frequent in healthy donors than in COVID-19 patients and was characterized by CD4+ T cells expressing early differentiation markers (CD62L+CD95+CD127+CD28+) and low levels of KLRG1 and CD56." (PMID 39136010, 2024). "Analysis of CD8+ T-cells showed that, despite the disease outcome, an increased frequency of CD69+ and CD107a+, along with a decreased percentage of CD28+, CD27+, and CD45RO+ CD8+ T-cell subsets, were observed in both COVID-19 subgroups." (PMID 39597661, 2024). "Despite no changes in the frequency of CD8+ T-cells, increased frequencies of CD69+, CD107a+, T-bet+, and CD62L− and decreased percentages of CD28+, CD27+, and CD45RO+ CD8+ T-cells were observed for COVID-19 patients in comparison to HCs." (PMID 39597661, 2024). "After adjusting for prior COVID-19, the estimated impact of frailty and age remained similar on CD8 + CD28- TEMRA cells (p = 0.056 and p = 0.31, respectively)." (PMID 36650551, 2023). "We found that increased pSTAT3 levels in both CD4 and CD8 T cells was associated with decreased production of IFN-γ in response to CD3/CD28 stimulation, suggesting increased STAT3 activation as a mechanism for defects in T cell function during COVID-19." (PMID 35421120, 2022). "Anti-CD28 agonistic antibodies were combined with inactivated SARS-CoV-2 to better activate T cell responses, particularly in convalescent COVID-19 patients." (PMID 35464396, 2022). "The proportion of EM (CCR7+, CD45RA−, CD28+ and CD27+/−) CD8+ T cells known to have higher concentration of GZMK is significantly decreased in the first week of COVID-19." (PMID 34945761, 2021). "Furthermore, staining the PBMCs of the COVID-19 convalescents with MHC-I multimers revealed that SARS-CoV-2-specific CD8+ T cells had effector memory (CD45RA−CCR7−) or central memory (CD45RA−CCR7+) phenotypes with early (CD27+CD28+) or intermediate (CD27+CD28−) differentiation." (PMID 34452355, 2021).
COVID-19 (continued). "These researchers demonstrated that the production of IFN-γ by peripheral blood T cells of COVID-19 patients was impaired as compared with T cells from healthy individuals and septic patients after anti-CD3/anti-CD28 antibody stimulation." (PMID 33995342, 2021). "Furthermore, there was increased detection of CD8 + CD28- TEMRA cells in individuals with greater frailty (p = 0.056, adjusted for COVID-19)." (PMID 36650551, 2023). "There was a negative association of CD8 + CD28- TEMRA cells with total antibody response to 2 vaccine doses (p = 0.027, r2 = 0.35 and p = 0.028, r2 = 0.81; unadjusted and adjusted for COVID-19 respectively)." (PMID 36650551, 2023). "Upon in vitro stimulation with anti-CD3/CD28 antibodies, CD4 T cells of COVID-19 patients showed a lower capacity to express IFNγ and IL-2 and proliferated together with the number of CFSElow cells (a measure of T-cell proliferation) compared to similar T-cell subsets of the control group." (PMID 35632823, 2022). "Therefore, in a pilot study we evaluated the effects of 5-FU in vitro by treating co-cultures of MACS sorted monocytic cells of 4 severe COVID-19 patients and purified allogeneic T cells in the presence of CD3/CD28 immunobeads." (PMID 33692788, 2021). "Amongst T-cell and monocytes/macrophages, some immune-stimulatory or auto-regulatory interactions were seen (CTLA4 or CD28/CD80 or CD86, CCL5/CCR5), but specific epithelial to T-cell interactions in critical COVID-19 were limited to pro-inflammatory ICAM1-mediated interactions." (PMID 33473155, 2021). "The cytokine storm syndrome in COVID-19 patients is mainly characterized by the IL-1 family, IL-6, and TNF-α, among which the serum TNF-α level is negatively correlated with T cell function by downregulating the expression of co-stimulatory molecule CD28." (PMID 33808998, 2021). "Inflammaging could exacerbate COVID-19 pathology and might even inhibit T cell responses to SARS-CoV-2 vaccines, due to downregulating the expression of T cell co-stimulatory molecule CD28." (PMID 33808998, 2021). "Next, patients with acute COVID-19 had elevated numbers of peripheral blood CD4+ T cells simultaneously producing IL-2 and IL-17 than healthy controls in response to in vitro stimulation with anti-CD3/CD28, pointing to effector Th skewing toward the Th17 phenotype." (PMID 36146622, 2022). "In the nonspecific activation with anti-CD3 and anti-CD28, IFN-γ was robustly secreted from T cells from age-matched unexposed controls or convalescent COVID-19 patients." (PMID 38424104, 2024). "Regardless of the disease outcome, decreased frequency of CD28+, CD38+, and CD62L− CD4+ T-cell subsets were observed in both COVID-19 subgroups." (PMID 39597661, 2024). "Similar to nonspecific anti-CD3/CD28 stimulation, SARS-CoV-2 S and N proteins may also lead to a state of immune exhaustion in T lymphocytes, with increased CD25 and CD62L and decreased PD-1 and TRAIL in convalescent COVID-19 patients." (PMID 38424104, 2024).
Sepsis (51 papers, 2009 to 2025). Sepsis is defined as life-threatening organ dysfunction caused by a dysregulated host response to infection. "Given the identification of CD8+ T cells as a critical cell subset underlying the ability of the CD28 agonist to improve sepsis survival, we next queried the effect of CD28 agonism on the CD8+ T cell compartment in memory septic mice." (PMID 38633258, 2024). "Specifically, CD127 on CD28+ CD45RA- CD8br T cells accounted for 5.296% of the increased risk of AP progressing to sepsis." (PMID 38601150, 2024). "HLA DR+ CD8br %T cells and CD127 on CD28+ CD45RA- CD8br T cells were linked not only to AP as an outcome but also as exposures in relation to sepsis." (PMID 38601150, 2024). "In contrast, CD127 on CD28+ CD45RA- CD8br T cell accounted for 5.296% of the increased risk of AP for sepsis." (PMID 38601150, 2024). "Downregulation of CD28 during inflammatory dysregulation is associated with outcomes following major trauma and sepsis." (PMID 37744382, 2023). "In conclusion, we found that the CD8+CD28+ T‐cell count is associated with early CMV infection in patients with sepsis and has predictive potential for CMV‐DNA–negative conversion and 28‐day mortality." (PMID 36106958, 2022). "Conclusions: 2B4 and CD28 expression on T cells were associated with 30-day mortality in ICU patients with sepsis." (PMID 34781995, 2021). "Our study, employing Mendelian Randomization, reveals a significant causal relationship between acute pancreatitis and specific immune cell traits, particularly highlighting that CD127 on CD28+ CD45RA- CD8br T cells contributes to 5.296% of the increased risk of sepsis in AP patients." (PMID 38601150, 2024). "Decreased expression of CD28 is considered to be a marker of T cell senescence, while CD28 + Treg cells enhance the role of immunosuppression, which may be the cause of increased risk of sepsis death." (PMID 39076981, 2024). "In an “immunologically experienced” murine model, CD28 agonism improved CLP sepsis survival in a CD8+ T cell–dependent manner and dampened systemic cytokine release." (PMID 41462924, 2025). "Among these, CD127 on CD28+ CD45RA- CD8+ T cells emerged as a common mediator, accounting for 5.296% of the increased risk of sepsis in AP patients." (PMID 38601150, 2024). "CD28 agonism during sepsis also led to increased IL-2 production from bulk CD8+ T cells, driven mainly by CD44hiCD8+ T cells." (PMID 38633258, 2024). "CD28 is one of T cell costimulatory molecules significantly altered on memory T cells during sepsis." (PMID 38633258, 2024). "Mechanisms by which patients become immunosuppressed during sepsis include upregulation of inhibitory molecules, expansion of the regulatory T cell population, and downregulation of CD28 and HLA-DR-mediated activation pathways." (PMID 38633258, 2024). "Taken together, these results indicate that CD28 agonism in immunologically experienced mice effectively suppresses inflammation via a CD8+-dependent mechanism to decrease mortality during sepsis." (PMID 38633258, 2024). "Recent studies found that PD-L1 expression on NK cells was associated with the prognosis of septic patients, and an elevated PD-1/CD28 ratio in CD8+ T cells predicted nosocomial infection in patients with sepsis." (PMID 39104530, 2024). "Given this possible role of CD28 in sepsis immunosuppression, multiple studies have found that modulation of CD28 and its ligands impact the emergence of immune dysregulation during sepsis, and thus impact mortality." (PMID 38633258, 2024). "This allowed us to also investigate the role of CD28 in a more physiologically relevant murine sepsis model." (PMID 38633258, 2024). "As detailed in Section 2.6 and Section 2.7 above, CD28 mimetic peptide p2TA protects mice from a wide variety of lethal infections and showed excellent safety in humans while protecting them from severe sepsis." (PMID 39456976, 2024).
Sepsis (continued). "This study addressed the role of CD28 signaling during sepsis-induced immune dysregulation in immunologically experienced hosts." (PMID 38633258, 2024). "The positive causal relationship between CD127 on CD28+ CD45RA- CD8br T cells and the onset of sepsis suggests that memory CD8+ T cells play a significant role in the progress of sepsis." (PMID 38601150, 2024). "CD66b+ cells isolated from sepsis patients 14-21 days after infection were capable of significantly suppressing CD8+ T-lymphocyte proliferation in response to CD3/CD28 stimulation." (PMID 38720891, 2024). "Wang established a mouse model of sepsis and found that plasma HMGB1 level was increased in mice with sepsis, while the expression of CD28 on the surface of CD4+T cells was inhibited, and the expression of PD-1 was increased." (PMID 39314628, 2024). "This analysis pointed out the central role played by CD28, which was the only miR-93-5p target downregulated after induction of sepsis in both models in this analysis: S. aureus (P < 0.05) and E. coli (P < 0.01)." (PMID 37261908, 2023). "Recent studies have shown that CD28 agonism can prolong the survival of CLP-induced immunologically experienced sepsis mice via IL-10 released by T cells." (PMID 37261908, 2023). "The CD8+CD28+ T‐cell count was the best predictor of CMV‐DNA–negative conversion potential in active CMV–infected patients with sepsis." (PMID 36106958, 2022). "Lastly, logistic regression and receiver operating characteristic curve analysis showed that the CD8+CD28+ T‐cell count was a better predictor of prognosis than the CD8+ T‐cell count for active CMV–infected patients with sepsis." (PMID 36106958, 2022). "It is worth noting that many of these proteins, such as MPO and CD28, have been reported to play a role in sepsis." (PMID 35739592, 2022). "A higher CD8+CD28+ T‐cell count is associated with incidence of active CMV infection and lower 28‐day mortality in patients with sepsis." (PMID 36106958, 2022). "The sensitivity and specificity of a CD8+CD28+ T‐cell count cutoff value of 64.5 cells mm−3 in predicting the 28‐day mortality of active CMV–infected patients with sepsis were 52.9% and 92.3%, respectively." (PMID 36106958, 2022). "The Kaplan–Meier analysis showed that active CMV–infected patients with sepsis with CD8+CD28+ T‐cell count < 64.5 cells mm−3 (log‐rank P < 0.001) were associated with a lower survival rate in the ICU." (PMID 36106958, 2022). "The mouse sepsis models confirmed two pathways that the ssNN missed: the CD28-dependent VAV1 pathway and the oxidative stress induced senescence pathway." (PMID 30629591, 2019). "In line with our findings, pathways involving T cell receptor and CD28 signaling as well as antigen presentations where massively down-regulated already early after sepsis onset." (PMID 29920518, 2018). "Previous work from our group has shown that expression of CD28 is decreased in both animals and patients with sepsis." (PMID 26786705, 2016). "In this regard, CD4 T cells from animals with sepsis that were treated with IL-7 had an increase in CD28 expression and improvement in T cell function." (PMID 26786705, 2016). "Two hours after sepsis, CLP had more significant expression of genes associated with IL-10 signaling pathways, whereas CS had greater expression of genes related to CD28, apoptosis, IL-1 and T-cell receptor signaling." (PMID 24788351, 2014). "At this stage, the only consistently observed difference was a tendentially or significantly stronger response to soluble CD3 and soluble CD3/CD28 mAb in T-cells from the SIRS/sepsis groups." (PMID 25541945, 2014). "Boomer observed that sepsis patients that develop an immunosuppressed status do not survive and show a significant reduction of the cytokine levels in splenocytes after LPS or anti-CD3/anti-CD28–stimulation in vitro compared with non-sepsis patients." (PMID 23799041, 2013).
Sepsis (continued). "In effect, it has been reported that patients with severe sepsis showed a significant reduction in T lymphocyte CD28 expression." (PMID 19243622, 2009). "We first wished to establish that CD28 was serving as the predominant ligand for CD80 or CD86 engagement in sepsis." (PMID 19672303, 2009). "The CD4+ T cell count, CD4+CD28+ T cell count, CD8+ T cell count and CD8+CD28+ T cell count were also significantly lower in elderly sepsis patients (194 versus 474, P<0.001; 180 versus 451, P=0.001;107 versus 199, P<0.001; 35 versus 132, P<0.001 respectively)." (PMID 40933998, 2025). "Additionally, MMP9 induced increased PD-1 expression on CD4+ T cells and reduced IL-2 and IFN-γ production upon anti-CD3/CD28 stimulation, confirming the association between MMP9 and CD4+ T cell exhaustion during sepsis." (PMID 41306770, 2025). "In contrast, another study showed antibody-mediated CD28 stimulation could be protective for intestinal immune responses during sepsis due to its role in T cell transendothelial migration." (PMID 38633258, 2024). "In the context of sepsis leading to 28-day mortality, our analysis showed that the relative count of CD28+ DN Treg cells within the T-cell population could increase the levels of the T-cell surface glycoprotein CD6 isoform." (PMID 39076981, 2024). "Results demonstrate a functional role of CD28 agonism during sepsis in immunologically experienced mice, which are likely more physiologically similar to immunologically experienced adult humans, as compared to naïve laboratory mice housed under specific pathogen-free conditions." (PMID 38633258, 2024). "Reports regarding the role of CD28 signaling in sepsis have been somewhat contradictory." (PMID 38633258, 2024). "Therefore, here we aimed to identify the cell subset(s) necessary for the survival benefit observed in the context of CD28 agonism, and to further investigate the mechanism by which CD28 agonism improves sepsis survival in immunologically experienced mice." (PMID 38633258, 2024). "A recent study using a mouse model of burn injury and sepsis has shown that Flt3L treatment mitigates T cell depletion, restores CD28 expression on CD4+ and CD8+ T cells, and increases IFN-γ production by CD8+ T cells, thereby reducing organ injury markers and enhancing survival." (PMID 39720718, 2024). "Thus, further investigation is needed to dissect the role of CD28 signaling on memory Treg cells during sepsis." (PMID 38633258, 2024). "In addition, stimulatory molecules such as CD28 and HLA-DR are significantly downregulated in sepsis, reflecting the host’s impaired ability to combat pathogens." (PMID 39720718, 2024). "Jointly with our previous findings, this current study indicates that CD28 agonism in immunologically experienced mice promotes the generation of an immunosuppressive environment that quells systemic inflammation and is beneficial for survival during sepsis." (PMID 38633258, 2024). "Because TGF-β is significantly upregulated during sepsis, our results are consistent with the hypothesis that CD28 agonism during sepsis directly increases a population of immunosuppressive CD8+ Foxp3+ T cells." (PMID 38633258, 2024). "The baboon sepsis models pointed out the membrane molecule CD28 in particular." (PMID 37261908, 2023). "The CD8+CD28+ T‐cell count may have been more accurate in predicting the 28‐day mortality after enrollment for active CMV–infected patients with sepsis." (PMID 36106958, 2022). "First, by comparing the immune parameters of all patients with sepsis, we found that CD8+CD28+ T cells may be an important related factor for active CMV infection in patients with sepsis." (PMID 36106958, 2022). "Regulating 2B4 and CD28 pathway was demonstrated to improve sepsis mortality in animal studies." (PMID 34781995, 2021). "Use of a CD28 mimetic peptide has been shown to increase survival in gram-negative and polymicrobial models of mouse sepsis and has been explored as a therapeutic option for human sepsis." (PMID 30629591, 2019).